HEXIM1 (HEXIM P-TEFb complex subunit 1)
Diseases named in the same sentence as HEXIM1 in open-access papers (continued):
Sharing a sentence is not in itself a finding about the gene and the disease.
AIDS (1 paper, 2024). A syndrome resulting from the acquired deficiency of cellular immunity caused by the human immunodeficiency virus (HIV). "Hexamethylene-bis-acetamide-inducing protein 1 (HEXIM1) has been identified as an inhibitor of positive transcriptional elongation factor b associated with cancer, AIDS, myocardial hypertrophy, and inflammation." (PMID 38363111, 2024).
Alzheimer disease (1 paper, 2026). A progressive, neurodegenerative disease characterized by loss of function and death of nerve cells in several areas of the brain leading to loss of cognitive function such as memory and language. "In this study, we found that neuronal expression levels of HEXIM1 mRNA are highly correlated with impaired cognition in Alzheimer's disease." (PMID 41759739, 2026).
atherosclerosis (1 paper, 2025). A disease characterized by the build-up of fatty material and calcium deposition in the arterial wall resulting in partial or complete occlusion of the arterial lumen. "We identified 12 lactylation-related genes that are more reliably associated with atherosclerosis: five upregulated genes (LSP1, IKZF1, MNDA, RCC2, and WAS) and seven downregulated genes (CSRP2, PPP1CB, CSRP1, HEXIM1, CALD1, PDLIM1, and RANBP2)." (PMID 40248193, 2025).
colon cancer (1 paper, 2021).
cyst (1 paper, 2022). A sac-like closed membranous structure that may be empty or contain fluid or amorphous material. "Compared to EGFP mRNA injection, infusion of WT human HEXIM1 mRNA dramatically reduced cyst development, while injection of S158E mutant HEXIM1 mRNA failed to protect the cystic kidney phenotype." (PMID 35878329, 2022).
invasive breast carcinoma (1 paper, 2009). A carcinoma that infiltrates the breast parenchyma. "In accordance with this finding, expression of Hexim1 was down-regulated in samples from invasive breast cancer patients in comparison to Hexim1 level in normal breast tissue." (PMID 19723344, 2009).
left ventricular hypertrophy (1 paper, 2012). Enlargement of the LEFT VENTRICLE of the heart. "Hexamethylene bis-acetamide inducible protein 1 (HEXIM1) is a negative regulator of positive transcription elongation factor b (P-TEFb), which activates RNA polymerase II (RNAPII)-dependent transcription and whose activation is strongly associated with left ventricular hypertrophy." (PMID 23300697, 2012).
multiple myeloma (1 paper, 2015). "Overexpression of HEXIM1 leads to limited availability of active P-TEFb as a result of sustained BET inhibition in myeloma cells having a significant impact on the transcription of a large number of genes, including oncogenic MYC." (PMID 25989842, 2015). "Our findings of increased HEXIM1 gene expression after treatment with OTX015 are in line with those reported with either JQ1 or I-BET151, in multiple myeloma and ALL." (PMID 25989842, 2015).
prostate adenocarcinoma (1 paper, 2022). "HEXIM1 expression is strongly correlated with TGFβ/SMAD expression and has been linked to poor survival outcomes in patients with prostate adenocarcinoma." (PMID 36291758, 2022).
schizophrenia (1 paper, 2025). A major psychotic disorder characterized by abnormalities in the perception or expression of reality. "In addition, HEXIM1 is an epigenetic-tagged gene in both PD and schizophrenia." (PMID 39905509, 2025).
cancer (19 papers, 2013 to 2025). A tumor composed of atypical neoplastic, often pleomorphic cells that invade other tissues. "Increased HEXIM1 expression caused differentiation and inhibited proliferation and metastasis of cancer cells." (PMID 31805991, 2019). "HMBA and its analogs induce hexamethylene bis-acetamide inducible protein I (HEXIM1) expression in cancer cells and achieve its biological activity." (PMID 37375314, 2023). "Involvement of a non-epigenetic mechanism should provide novel insight into the regulation of HEXIM1 expression in cancer cells." (PMID 33273553, 2020). "Our findings also have important implications for the development of small molecules or other strategies to induce the expression of HEXIM1 as therapeutic options against cancer." (PMID 33273553, 2020). "As a measure of the functional relevance of the induction of HEXIM1 expression by 5-AzadC, we examined the expression of p21, which was upregulated by HEXIM1 during HEXIM1-induced cancer cell differentiation." (PMID 33273553, 2020). "HEXIM1 also plays a central role in the anti-cancer activities of another category of therapeutics, BET inhibitors." (PMID 31805991, 2019). "We tested the possibility that while KDM5B and its inhibitors likely regulate other targets, HEXIM1 is a critical mediator of the anti-cancer effects of KDM5B inhibitors." (PMID 31805991, 2019). "The simultaneous targeting of multiple pro-cancer pathways by HEXIM1 improves the likelihood of sustained effect by limiting the cancer cell’s ability to bypass the inhibition of any one pathway." (PMID 31805991, 2019). "For the lymphoid-derived cancer cell lines next to the specific surface markers (e.g., CD72, LAIR) associated with T/B-cells, we identified FLT3, HOXA9, MYC, and HEXIM1 as top genes driving the difference between the samples." (PMID 31253180, 2019). "HEXIM1 inhibits tumor growth and metastasis by inducing cancer cell differentiation and inhibiting cell proliferation and invasion, angiogenesis, and the premetastatic niche." (PMID 31805991, 2019). "Of those, antibodies targeting the proteins orthodenticle homeobox 1 (Otx1) and hexamethylene bisacetamide inducible protein 1 (Hexim1) were of sufficient quality for validation in PyMT carcinoma sections." (PMID 31505876, 2019). "Consistent with a decrease at the mRNA level, the Hexim1 protein was expressed at high levels in fibroblasts in the early stage, but its expression was low in late-stage carcinoma CAFs." (PMID 31505876, 2019). "It will be important for cancer researchers to further investigate the relationship between HEXIM1, replication stress, and the response to cancer treatment." (PMID 30463005, 2018). "Recent evidence demonstrated a role of HEXIM1 in cancers via regulation of P-TEFb dependent mechanisms." (PMID 28484091, 2017). "HEXIM1 exhibits its anti-cancer effects through the inhibition of the ERα-dependent gene expression." (PMID 26734838, 2016). "Here we will discuss the current knowledge on Brd4 and HEXIM1 and their implication as novel therapeutic options against cancer." (PMID 24592384, 2014). "In this review, we will focus on the recent findings on Brd4/HEXIM1 with respect to their newly discovered roles in cell cycle progression and cancer." (PMID 24592384, 2014). "Involvement of Brd4 and HEXIM1 in tumorigenesis through the P-TEFb-dependent and -independent mechanisms opens a new and exciting venue for cancer research." (PMID 24592384, 2014).
cancer (continued). "HEXIM1 was proposed as a mediator of HMBA actions in cancer cells." (PMID 37984341, 2023). "The anti‐cancer effects of HMBA are mediated mostly by HMBA‐inducible protein 1 (HEXIM1)." (PMID 37984341, 2023). "Because of the well-known role of DNMT1 in the inhibition of the expression of tumor suppressor genes, we determined if DNMT1 inhibitors could be utilized to re-express HEXIM1 in cancer cells." (PMID 33273553, 2020). "Thus, HEXIM1 induction is an intriguing therapeutic approach to cancer treatment, but requires better chemical tools than HMBA." (PMID 31805991, 2019). "Moreover, our findings were corroborated by a Cancer Outlier Profile Analysis (COPA) of existing microarray data, showing HEXIM1 is downregulated and a potential tumor suppressor in breast, prostate, and other cancers." (PMID 31805991, 2019). "Taken together, we demonstrate the potential use of the HEXIM1 BR peptide in cancer therapy." (PMID 26734838, 2016). "The potential involvement of HEXIM1 in cancers was first reported in 2003." (PMID 26734838, 2016). "The HEXIM1 BR peptide did not cause any cytotoxic effect when it was not fused with a cell-penetrating (i.e. FGF) or cancer cell targeting (i.e. LTV) peptide." (PMID 26734838, 2016). "The potential involvement of HEXIM1 in cancers was first reported by Montano and coworkers in 2003." (PMID 24592384, 2014). "Development of small molecules or other strategies to block the chromatin-binding of Brd4 or to induce the expression of HEXIM1 may provide novel therapeutic options against cancer." (PMID 24592384, 2014). "In this review, we will summarize our findings and discuss the role of HEXIM1 in cancer." (PMID 24202322, 2013). "Although it is largely unknown whether HEXIM1 expression is also upregulated in cancer cells with constitutive upregulation of P-TEFb expression and activity, it is fascinating to speculate that there is a specific mechanism to alleviate this negative feedback system in cancer cells." (PMID 32075058, 2020). "The CDK9-inhibiting module from HEXIM1 could indeed be combined with functional domains from transactivator targets other than Tat, allowing this strategy to be applied to other pathologies, including inflammation or cancer." (PMID 30395647, 2018). "This analysis focused on the functionally significant components of the multimeric RNAPII complex, including BRD4, HEXIM1, Spt5, NELF-A, Cyclin T, CDK9, LARP-7, and Caspase-8, which collectively serve as a regulatory hub in gene expression in cancer cells." (PMID 38201534, 2023). "RNA-seq analysis after 4 h of in vitro treatment, demonstrated that pathway modulation (HEXIM1) was strongly increased upon the combination of BI 894999 (10 nM) and CCS1477 (300 nM) vs mono-treatment in all four NUT carcinoma cell lines." (PMID 35444289, 2022). "Since HEXIM1 BR peptide severely damages the fundamental biological function essential to all cell types, we reason that the peptide could be utilized in the development of novel treatment against drug-resistant cancer guided by a specific cancer targeting peptide." (PMID 26734838, 2016). "Of note, we conducted an analysis of HEXIM1 expression, a gene that has consistently exhibited a robust and consistent modulation in response to Bromodomain and Extra terminal domain (BET) inhibitors across diverse cancer indications." (PMID 38201534, 2023).
cancer (continued). "As untagged HEXIM1 BR peptide is unable to kill cells when it is not fused with any cell-penetrating or targeting peptides, our data suggest that HEXIM1 BR peptide may be a safer alternative as compared to KLA, for the development of anti-cancer therapeutics." (PMID 26734838, 2016). "Besides miR-17 target genes altered during early-stage cancer include TSC1 and HEXIM1." (PMID 31756185, 2019).
tumor (14 papers, 2011 to 2025). "We have been studying the role of HEXIM1 as a tumor suppressor whose expression is lost during breast and prostate tumor progression and metastasis." (PMID 31805991, 2019). "We previously reported that a functional interaction between KDM5B and the tumor suppressor, HEXIM1, is required for HEXIM1 inhibition of nuclear hormone receptor activity." (PMID 31776402, 2019). "The data showed higher HEXIM1 expression in ubenimex-treated tumor tissues (P=0.015), which was consistent with in vitro studies." (PMID 28484091, 2017). "Our findings suggest the potential of ubenimex adjuvant treatment to enhance JQ1 efficiency and attenuate parts of its side effect (enhancing tumor aggressive) by regulating the autophagic degradation of HEXIM1 and Akt inhibition." (PMID 28484091, 2017). "Retroviral insertions were present in the mouse homologs of 10 genes tagged in the zebrafish tumor samples: Brd2, Cirbp, Fgf8, Hexim1, Map2k5, Mmp14, Ncoa2, Slc30a5, Sox4, and Sox5." (PMID 21533036, 2011). "Mechanistic studies pointed to a role in transcriptional elongation; HEXIM1 normally acts through positive transcription elongation factor (p-TEFb) to inhibit transcription of tumor-promoting genes and stabilize transcription of other tumor suppressor genes." (PMID 32455885, 2020). "Taken together, these results suggest the tumor suppressor function of HEXIM1." (PMID 24592384, 2014). "PLGA-mediated delivery of KDOAM25 induced increases in HEXIM1 expression in the mammary gland, as well as decreases in tumor weights, although the decrease was not statistically significant." (PMID 31805991, 2019). "The most significant increase (p=6.68×10−257) of a gene after high intensity treatment that was not increased at low intensity treatment occurred in Hexim1, a transcriptional elongation factor that has been shown to suppress tumor growth in response to nucleotide stresses." (PMID 32175843, 2020).
infection (5 papers, 2012 to 2024). The state of being infected such as from the introduction of a foreign agent such as serum, vaccine, antigenic substance or organism. "Also, the virus proliferation deficiency caused by US1 deletion during the early infection stage could be partially rescued by HEXIM1 overexpression, suggesting that HEXIM1 is responsible for the transcription advantages of AnHV-1 when competing with cells." (PMID 38363111, 2024). "This indicates that HEXIM1 expression is related to the disease infection process and exhibits different regulation patterns in various tissues." (PMID 38363111, 2024). "Additionally, the virus proliferation deficiency caused by US1 deletion during the early infection stage could be partially rescued by HEXIM1 overexpression, suggesting that HEXIM1 is responsible for AnHV-1 gaining transcription advantages when competing with cells." (PMID 38363111, 2024). "The infection of AnHV-1 BAC after HEXIM1 overexpression was significantly higher than that in the control group at the same time point." (PMID 38363111, 2024). "The expression of HEXIM1 in the thymus, brain, and liver was successively upregulated by AnHV-1 during the first 3 days of infection, while the opposite trend was observed in the liver (increased) and thymus (decreased) on day 5 post-infections." (PMID 38363111, 2024). "Moreover, this discovery expands the significance of HEXIM1 in pathogen infection." (PMID 38363111, 2024). "As expected, the high expression of HEXIM1 induced by AnHV-1 promotes the formation of HEXIM1-CDK9 complexes in a virus dose- and infection time-dependent manner." (PMID 38363111, 2024). "In this case, NEAT1, which is upregulated by infection, associates with HEXIM1, DNA-PK, and paraspeckle proteins (SFPQ, NONO, PSPC1, RBM14, and MATRIN3) to form a complex named HEXIM1-DNA-PK-paraspeckle components ribonucleoprotein(HDP-RNP)." (PMID 38717150, 2024). "Moreover, exogenous expression of not mtHEXIM1 but HEXIM1 counteracted with tropic effect of ET-1 on NRCM size in a multiplicity of infection (MOI)-dependent manner." (PMID 23300697, 2012).
HEXIM1 also shares sentences with these, for which no sentence is quoted: acute leukemia (2 papers); asthma (2); triple-negative breast carcinoma (2); adenocarcinoma (1); cardiovascular disease (1); cystic kidney (1); heart failure (1); HIV-1 infection (1); Hypertension (1); hypertrophy (1); leukemia (1); NUT carcinoma (1); pulmonary hypertension (1); squamous cell carcinoma (1); Stroke (1).